PVT1 (Pvt1 oncogene)
Diseases named in the same sentence as PVT1 in open-access papers (continued):
Sharing a sentence is not in itself a finding about the gene and the disease.
colon carcinoma (38 papers, 2012 to 2026). "Increased PVT1 expression is linked to colon cancer incidence, disease remission, and distant metastasis." (PMID 38166659, 2024). "One study linked miR-30d-5p with carcinogenesis in colon cancer through the long non-coding RNA, PVT1." (PMID 35155437, 2022). "LncRNA PVT1 transcription site is located in a cancer susceptibility locus downstream of Myc, and ablation of PVT1 from MYC-driven colon cancer line HCT116 diminished its tumorigenic potency." (PMID 36266267, 2022). "We observed that the regulatory mechanism of the miR-152-3p/PVT1/VEGFA axis causes metastasis in colon cancer through the overexpression and inhibition of miR-152-3p in colon cells." (PMID 34336125, 2021). "Exosomal PVT1 promotes colon cancer metastasis through its association with EGFR and VEGFA expression." (PMID 34336125, 2021). "In this study, we examined plasmacytoma variant translocation 1 (PVT1), an lncRNA locus, which has been identified as a candidate oncogene in several types of tumor, including colon cancer tumors." (PMID 34336125, 2021). "Computational analysis was performed to determine genes associated with the exosomal long noncoding (lncRNA) plasmacytoma variant translocation 1 (PVT1)/vascular endothelial growth factor A (VEGFA) axis in patients with colon cancer." (PMID 34336125, 2021). "LncRNA plasmacytoma variant translocation 1 (PVT1) boosts colon cancer progression by sponging miR-26b." (PMID 32694944, 2020). "From our literature review, we found that several lncRNAs among the ceRNA network, such as lncRNAs UCA1, GAS5, MALAT1, and PVT1, are associated with oncogenesis and the development of colon cancer." (PMID 30984308, 2019). "Very recently, it was demonstrated that the polymorphisms of miR-146a (rs2910164) and plasmacytoma variant translocation 1 (PVT1; rs13281615) affect the prognosis of colon cancer by regulating COX-2 expression and cell apoptosis." (PMID 31379585, 2019). "Cytoplasmic lncRNA PVT1 (plasmacytoma variant translocation 1) has been found to act as a competitive endogenous RNA (ceRNA) against miR-214-3p and promote the progression of colon cancer." (PMID 32460771, 2020). "Since loss of PVT1 RNA in colon cancer cell line reduces MYC protein to more normal levels, inhibiting PVT1 could be a more accessible and feasible therapeutic strategy for renal cancer." (PMID 27366943, 2016). "Relevant studies revealed that PVT1 is an oncogene that facilitates the evolvement of colon cancer though the miR-30d-5p/RUNX2 axis." (PMID 35155437, 2022). "We examined the functional roles of PVT1 in colon cancer by silencing PVT1 through the siRNA technique." (PMID 34336125, 2021). "We found that patients with colon cancer (GSE17537) with higher PVT1 expression had significantly shorter overall and disease-free survival durations." (PMID 34336125, 2021). "The results of this study indicated the potential role of PVT1/VEGFA-enriched serum exosomes in promoting distant metastasis in colon cancer." (PMID 34336125, 2021). "Because we noted an increased PVT1 level in the tissue or serum samples of patients with colon cancer, we analyzed serum exosomes isolated from these patients." (PMID 34336125, 2021). "At present, the carcinogenic effect of PVT1 has been confirmed in various cancers such as gallbladder, non-small-cell lung, and colon cancers." (PMID 34336125, 2021). "Our comparative experiments performed using M-exo and P-exo revealed that M-exo not only contained a significantly higher PVT1 level than did P-exo but also enhanced the migratory and invasive abilities of the human colon cancer cell lines HCT116 and LoVo." (PMID 34336125, 2021). "PVT1 depletion in HCT 116 colon cancer cells dramatically compromised their ability to form tumors, as high MYC protein levels are dependent on PVT1." (PMID 32602581, 2020).
colon carcinoma (continued). "HCT116 colon cancer cells resistant to the combination of 5-FU and radiation displayed increased levels of PVT1 compared to the parental cell line when evaluated using a human lncRNA Expression Array." (PMID 32083000, 2020). "In another study, PVT1 was reported to enhance cell migration and invasion via the modulation of miR-26b and miR-30d-5p in colon cancer cells." (PMID 33246471, 2020). "On the contrary, the PVT1 downregulation in the MYC-driven colon cancer cell line HCT116 reduced its tumorigenic potential, indicating a direct role of PVT1 in controlling MYC abundance." (PMID 29165379, 2017). "PVT1 expression is also increased in colon cancer patients and increasedexpression predicts poor prognosis." (PMID 27508057, 2016). "In the present study, we identified PVT1 as a prognostic biomarker in patients with colon cancer." (PMID 34336125, 2021). "Moreover, the downregulation of PVT1 significantly suppressed the metastatic ability of colon cancer cells, and PVT1 was observed to be regulated by the tumor suppressor miR-152-3p." (PMID 34336125, 2021). "PVT1 is reported to facilitate cell growth and invasion of colon cancer cells via Lin28/let-7 axis." (PMID 34229645, 2021). "In addition, studies have shown that removal of PVT1 (ranked 5) from MCY-driven colon cancer strain HCT116 can reduce carcinogenicity." (PMID 34490041, 2021). "Also, previous research suggests that PVT1 can sponge miRNA miR-26b and promote proliferation and metastasis of colon cancer." (PMID 33745450, 2021). "LncRNA plasmacytoma variant translocation 1 (PVT1) expression is remarkably increased in colon cancer tissues and correlates with lymph node metastasis, clinical stages and survival time in patients with colon cancer." (PMID 33246471, 2020). "lncRNA PVT1 functions as an oncogene in human colon cancer, which could promote the metastasis and proliferation of colon cancer by suppressing miR-30d-5p." (PMID 30984308, 2019). "Taken together, we speculated that these prognosis-related mRNAs may play roles in colon cancer by interacting with PVT1." (PMID 31612869, 2019). "In addition, PVT1 overexpression in colon cancer cells significantly promoted cisplatin resistance in vivo." (PMID 30984308, 2019). "Likewise, the expression of long noncoding RNA (lncRNA) PVT1, the host gene of miR‐1207‐5p was found to be approximately 9‐fold and 20‐fold higher in colon cancer HT‐29 and HT‐116 cells, respectively, compared to normal human colonic epithelial cells, HCoEpiC." (PMID 26990997, 2016). "The PVT1 gene is encoding for a non-translated RNA and has been found to be implicated in diabetic nephropathy and breast and colon cancer, in translocations related to Burkitt's lymphoma and associated with Hodgin's lymphoma." (PMID 22319602, 2012). "Of them, 14 lncRNAs are verified in databases C and D. found that lncRNA PVT1 increases MYC protein level, which in turn increases the cancer rate of colon cancer." (PMID 37614816, 2023). "M-exo were enriched with PVT1 and VEGFA, and both migratory and invasive abilities of colon cancer cell lines increased when they were cocultured with M-exo." (PMID 34336125, 2021). "PVT1 acts as a ceRNA to negatively regulate the expression of miR-455 in HT29 and SW480 colon cancer cell lines." (PMID 32083000, 2020). "Accordingly, both PVT1 and miR-214-3p sustained the expression and activation of PI3K catalytic subunit (p110) and Akt in colon cancer cell line models." (PMID 32083000, 2020). "Assessment of PVT1 transcript levels by quantitative RT-PCR in LOVO and RKO colon cancer cell lines with acquired resistance to cisplatin, or HCT8 and HCT116 with secondary resistance to 5-FU also evidenced the transcriptional upregulation of PVT1 lncRNA." (PMID 32083000, 2020).
colon carcinoma (continued). "Moreover, cell line experiments exhibited increased PVT1 levels in HT29 colon spheres compared with their parental counterparts along with increased VEGFA and EGFR levels, the two major metastatic or oncogenic markers in colon cancer." (PMID 34336125, 2021). "Furthermore, the analysis of 450 patients with colon cancer from the database of TCGA revealed a negative correlation between the expression of PVT1 and that of miR-152-3p (coefficient r value = −0.149 and p = 1.58E − 03)." (PMID 34336125, 2021). "Notably, a negative correlation between the expression levels of PVT1 and miR-152-3p was identified in TCGA colon cancer database consisting of 450 patient samples." (PMID 34336125, 2021).
non-small cell lung carcinoma (37 papers, 2016 to 2025). A group of at least three distinct histological types of lung cancer, including non-small cell squamous cell carcinoma, adenocarcinoma, and large cell carcinoma. "PVT1 is known as an oncogene, some evidence has indicated that PVT1 is upregulated in non-small cell lung cancer tissue, and its upregulation is associated with lymph node metastasis." (PMID 28938549, 2017). "The long non-coding RNA PVT1 is known to inhibit the expression of theLATS2 gene in non-small cell lung cancer cells by recruitingEZH2 (a subunit of the PRC2 complex) to the corresponding promoter." (PMID 40771853, 2025). "The interaction of PVT1 with miR-200 family is another example of what it has been shown that miR-200a and miR-200b are direct targets of PVT1 in non-small cell lung cancer." (PMID 36624401, 2023). "By regulating the miR-29c/vascular endothelial growth factor (VEGF) signaling pathway, PVT1 promotes angiogenesis in non-small-cell lung cancer (NSCLC)." (PMID 35634481, 2022). "In non-small cell lung cancer, lncRNA PVT1 induced radioresistance through miR-424-5p/CARM1, while CARM1 (coactivator associated arginine methyltransferase 1) is involved in DNA packaging, transcription regulation, pre-mRNA splicing, and mRNA stability." (PMID 35600868, 2022). "On the contrary, miR-361-3p was found to be decreased by lncRNA PVT1 in non-small cell lung cancer to affect cancer cell growth and metastasis." (PMID 34249085, 2021). "PVT1-mediated suppression of tumor radiosensitivity has been reported in non-small cell lung cancer, and NPC, respectively." (PMID 31320749, 2020). "For example, PVT1 facilitates HIF-1α expression through acting as ceRNA for miR-199a-5p in non-small cell lung cancer." (PMID 30894138, 2019). "Recent studies indicated that down-regulation of PVT1 expression inhibited non-small cell lung cancer cells proliferation, migration and invasion through epigenetically regulating large tumor suppressor 2 (LATS2) expression." (PMID 29348896, 2017). "In non-small-cell lung cancer cell lines, lncRNA PVT1 can bind to miR-424-5p to decrease the expression of factors in tumor progression, such as CRAM, MMP-2, MMP-9 and Bcl2, to inhibit growth and increase the expression of Bax, thus suppressing the development of tumor cells." (PMID 35409396, 2022). "Although growing evidences have showed that long non-coding RNA (lncRNAs) plasmacytoma varianttranslocation 1 (PVT1) plays a critical role in the progression of non-small cell lung cancer (NSCLC), there are still manyunsolved mysteries remains to be deeply elucidated." (PMID 33650817, 2021). "LncRNA PVT1 accelerates the oncogenesis of non-small-cell lung cancer through regulating miR-497." (PMID 32370736, 2020). "Coincidentally, the lncRNAs plasmacytoma variant translocation 1 (PVT1), diGeorge syndrome critical region gene 5 (DGCR5), and cytoskeleton regulator RNA (CYTOR) were confirmed to decrease the radiosensitivity of non-small cell lung cancer cells by sponging miR-195." (PMID 31391206, 2019). "Knockdown of PVT1 to a certain extent enhances the radiosensitivity of non-small cell lung cancer cells through inhibiting cell proliferation and promoting apoptosis, which provides a new therapeutic target for improving the efficiency of radiotherapy in patients with non-small cell lung cancer." (PMID 31309249, 2019). "PVT1 could be a novel biomarker for diagnosis and prognosis of non-small cell lung cancer." (PMID 28938549, 2017). "For example, concomitant overexpression of PVT1 and upregulation of HIF-1a has been shown in hypoxic non-small cell lung cancer." (PMID 31249809, 2019).
bladder cancer (34 papers, 2015 to 2025). "One study that investigated the relationship between PVT1 and bladder cancer found that PVT1 levels were significantly higher in bladder cancer tissue and were associated with clinical progression and poor prognosis." (PMID 36605618, 2023). "Experiments revealed that PVT1 has a significant regulatory effect on bladder cancer (BC) and can be used as a clinical diagnostic marker and a therapeutic molecular marker for patients suffering from BC." (PMID 33188158, 2020). "PVT1 is located at chromosome 8q24, a well-acknowledged risk locus for cancer and was promoted in bladder cancer tissue and linked to advanced histological grades and higher tumor stage in addition to lymph node metastases." (PMID 32293498, 2020). "Another study reported that lncRNA and MDM2 influence cancer progression through ubiquitination in bladder cancer, particularly investigating the mechanism by which lncRNA plasmacytoma variant translocation 1 (PVT1) regulates adriamycin (ADM) resistance in bladder cancer cells." (PMID 40771930, 2025). "Another lncRNA PVT1 has been proven to accelerate malignant phenotypes of bladder cancer cells via the overactivation of the WNT/β-catenin pathway." (PMID 38695942, 2024). "Expression of CDK1 has also been found to be increased in bladder cancer cells, parallel with over-expression of the long non-coding RNA (lncRNA) PVT1." (PMID 36266723, 2022). "Nevertheless, the intrinsic and concrete molecular mechanism of PVT1 in bladder cancer still remained unclear, which is also the dilemma faced in many non-coding RNA studies." (PMID 33188158, 2020). "Correlation between PVT1 expression and clinicopathological characteristics of bladder cancer patients." (PMID 33188158, 2020). "Through experiments such as loss-function and over-expression, the biological effects of PVT1 and miR-194-5p on the proliferation, migration, apoptosis and tumorigenicity were explored in bladder cancer cells." (PMID 33188158, 2020). "Co-immunoprecipitation, proteomics experiments, dual luciferase reporter gene analysis, western blot and other methods were adopted to investigate the PVT1 potential mechanism in bladder carcinomas." (PMID 33188158, 2020). "We reported the mutual correlation between PVT1 and miR-194-5p as miRNAs sponges in the bladder carcinomas." (PMID 33188158, 2020). "So far, numerous studies have showed that lncRNAs are involved in bladder cancer development and progression, such as PVT1, ZEB2NAT, MDC1-AS and growth arrest-specific 5 (GAS5)." (PMID 30042171, 2018). "The results showed that si-PVT1 suppressed cell growth significantly in bladder cancer cells (p < 0.001 in two cell lines)." (PMID 26517688, 2015). "shRNA sequences targeting PVT1 controlled by synthetic “tetracycline-on” switch suppressed the expression of PVT1 in response to different concentration of doxycycline and inhibited progression of bladder cancer." (PMID 26517688, 2015). "To further understand the biological roles of PVT1 in bladder cancer, we used the CCK8, EdU assays and cell apoptosis assays to detect cell growth and apoptosis in bladder cancer cells through silencing PVT1." (PMID 26517688, 2015). "In this study, we found that PVT1 was upregulated in bladder cancer tissues and cells, and functioned as an oncogene in bladder cancer." (PMID 26517688, 2015). "Compared with the SV-HUC-1 cell line, the PVT1 expression was increased significantly in bladder cancer cells, T24 (P < 0.01) and 5637 (P < 0.001)." (PMID 26517688, 2015). "Synthetic “tetracycline-on” switch system can be used to quantitatively control the expression of PVT1 in bladder cancer in response to different concentration of doxycycline to suppress the progression of bladder cancer." (PMID 26517688, 2015).